CD4 (CD4 molecule)
Diseases named in the same sentence as CD4 in open-access papers (continued):
Sharing a sentence is not in itself a finding about the gene and the disease.
AIDS (continued). "Participants were randomly assigned either to receive AZT immediately or to defer treatment until they developed AIDS symptoms or had persistently low CD4 counts." (PMID 39450053, 2017). "With the development and application of combination ART (cART), survival in HIV-infected adults has been extended by suppression of virus to undetectable levels and restoration of CD4+ T cell numbers to normal levels, thus preventing onset of AIDS." (PMID 29259605, 2017). "96.6% (n = 28) of the patients that died had less than 50 CD4 cells/μL, 80% (n = 24) had been admitted for an AIDS-defining illness, and 36.6% (11 patients) had two or more OIs." (PMID 29132400, 2017). "Some participants reported when they had knowledge about HIV/AIDS and associated self-care, they actively took part in HIV care (e.g., CD4 testing)." (PMID 28302106, 2017). "As a subset of memory CD4 T cells, Tfh cells were expected to undergo progressive depletion during AIDS." (PMID 28265271, 2017). "A stage 3 classification was defined as having a CD4 count of <200/μL, CD4 percentage of total lymphocytes of <14, or documentation of an AIDS-defining condition ≤3 months after a diagnosis of HIV infection." (PMID 28151924, 2017). "Specifically, we showed that chronic HPV levels were maintained at- i) AIDS level CD4+ T cell count and ii) inefficient drug therapy, εRT = 0.2 and εPI = 0 with intermediate CD4+ T cell levels such that T ̄ ≤ 2.6×105 cells." (PMID 28060843, 2017). "Most participants had CD4 counts above 500 cells/μl (51.5%) and viral loads below 400 copies/ml (75.7%) at enrollment; 41.6% of participants had been diagnosed with AIDS." (PMID 28893321, 2017). "We also found six independent factors associated with pre-treatment HIV RNA <100,000 copies/mL: age, BMI, anemia, CD4 count, total lymphocyte count, and prior AIDS-defining illness." (PMID 28484509, 2017). "The two main criteria in treatment guidelines for determining when to start treatment have been symptoms of AIDS and CD4 T-lymphocyte count." (PMID 39450053, 2017). "These women progressed to AIDS slightly faster than typical progressors, with a median time to CD4+ T cell counts below 200 mm3/uL of 6.0 years; time to CD4+ T cell counts below 200 mm3/uL was a median of 7.3 years in the 11 MACS participants studied herein." (PMID 29045410, 2017). "We find that CRPA correlates with CD4 counts, AIDS phenotype and CD4 T cell apoptosis in HIV patients." (PMID 28331180, 2017). "Hyponatremic HIV patients had a lower CD4 cell count, a higher prevalence of AIDS and were more frequently hospitalized at first contact compared to normonatremic patients." (PMID 28122494, 2017). "Studies that followed patients for mortality from ART start have found that the dominant prognostic marker is CD4 count and the majority of deaths are AIDS related." (PMID 28903507, 2017). "We used two AIDS Indicator Surveys52, 53 to predict the age-sex-CD4 cell distribution of ART coverage and applied the distributions to the input counts of people receiving ART in our HIV estimation model." (PMID 28919118, 2017). "Current antiretroviral therapy (ART) for HIV/AIDS slows disease progression by reducing viral loads and increasing CD4 counts." (PMID 28785069, 2017). "Late presentation (CD4 cell counts <350 cells/mm3 or CDC stadium AIDS) was identified in 10.1% (n =949/9363) of newly diagnosed cases with DSS/DPS with available data." (PMID 28693564, 2017). "The interviews indicated that time to next appointment varied depending on psychosocial and physical comorbidities, and clinical factors (time since diagnosis, AIDS diagnosis, treatment status, CD4 count and viral load)." (PMID 27535219, 2017). "Similar to the case of HIV/AIDS, idiopathic CD4+ T cell lymphocytopenia has also been shown to increase TB susceptibility and its associated mortality." (PMID 28646367, 2017).
AIDS (continued). "Stage 3 classification at diagnosis of HIV infection was defined as having a CD4 lymphocyte count of <200/μL, CD4 percentage of total lymphocytes of <14, or documentation of an AIDS-defining condition ≤3 months after a diagnosis of HIV infection." (PMID 28934185, 2017). "A higher proportion of the patients starting darunavir or lopinavir had a CD4 cell count below 200/μL, and together with raltegravir a higher proportion also had an AIDS diagnosis at start of treatment." (PMID 28207816, 2017). "Incidence of TB was found to be associated with sex, employment status, baseline WHO stage of HIV/AIDS and CD4 count." (PMID 28049455, 2017). "The study used the 2010 WHO criteria for starting treatment, which involved initiation of ART at a CD4 count less than 200 cells per μL or after development of an AIDS-defining event." (PMID 28063815, 2017). "For example, while some individuals have been observed to develop profound CD4+ T cell lymphopenia and AIDS within 2 years, others remain AIDS-free for up to 15 years following HIV seroconversion." (PMID 28695282, 2017). "Estimated monthly probability of occurence of AIDS defining illnesses according current CD4+ cells count." (PMID 29131849, 2017). "Access to CD4+ testing remains a common barrier to early initiation of antiretroviral therapy among persons living with HIV/AIDS in low- and middle-income countries." (PMID 29159139, 2017). "Data from a recent meta-analysis estimated that over half of patients in Africa had progressed to AIDS with CD4 counts <200 cells/mm3 by the time they initiated ART, despite over a decade of ART program implementation and scale-up." (PMID 28662028, 2017). "Among those who have ever received ART, approximately 37% initiated therapy with an AIDS-defining CD4 count (< 200 cells/mm3)." (PMID 28241797, 2017). "The decade-old National AIDS Control Program still relies on immunological monitoring, wherein six-monthly CD4 cell count measurements are performed, while PVL estimation is only reserved for confirmation of first-line ART failure." (PMID 28763465, 2017). "The median of CD4+ T cell counts in the AIDS group was much lower than that in the OTR, NHNT-1, or NHNT-2 groups, with statistical significance (median, 18 vs 270, 214, and 663; P < .001)." (PMID 28035481, 2017). "CD4 T lymphocytes that support HIV-1/SIV replication are central to the development of AIDS-defining illness as well as to the establishment of cell-associated viral reservoirs that persist despite years of antiretroviral therapy." (PMID 28654687, 2017). "Regular surveillance of HIV-1 subtypes and CD4 count would be beneficial in monitoring HIV/AIDS progression, as well as for improving personalized disease management and clinical counselling." (PMID 28484257, 2017). "Instead, ART initiation was guided by immunologic and/or clinical criteria, being indicated for patients with a CD4+ T-lymphocyte cell count < 200 cells/mm3 or with clinical manifestations of AIDS." (PMID 28348602, 2017). "In immunocompromised individuals such as AIDS patients, especially when CD4 cell count is under 150/mm3, Hcc can produce a DH involving various organs, such as: liver, spleen, bone marrow, lymphnodes, gastrointestinal tract and central nervous system." (PMID 28476105, 2017). "The median HIV RNA of the newly diagnosed patients was 225,910 copies/mL, the median CD4 was 357 cells/μL, and 29% had AIDS at presentation." (PMID 28744377, 2017). "Among 2NRTI+PI-treated patients AIDS history was notably more common while baseline and nadir lymphocyte CD4 counts were lower compared to 2NRTI+InI, with similar last lymphocyte CD4 count and baseline HIV-1 viral loads." (PMID 28715160, 2017). "Overall, 68.4% of patients in our study initiated ART with a CD4+ T-lymphocyte count < 200 cells/mm3 or clinical manifestations of AIDS, 72.5% of whom initiated ART in 2001 and 2002." (PMID 28348602, 2017).
AIDS (continued). "In Europe, 54% of newly diagnosed HIV-infected individuals were late presenters as defined by having CD4+T cell counts below 350cells/μL or an AIDS-defining illness within six months of HIV diagnosis." (PMID 28793312, 2017). "Progressors proceeded to AIDS-related death, while LTNPs maintained stable (drop of less than 10%) blood CD4+ T cell levels over 4 years of observation after enrollment in the cohort." (PMID 29184023, 2017). "This immunological threshold is clinically important in view of the fact that patients who regain their CD4 to this immunological point have a better clinical outcome with non AIDS events almost comparable to normal populations." (PMID 28595630, 2017). "One (X176) was reported to have a CD4+ T cell count of 115 cells/μl, which represents an AIDS-defining criterion, while the other (X284) maintained low viral loads and normal CD4 counts 16 years after infection." (PMID 28576126, 2017). "Chronic untreated HIV infection leads to extensive depletion of the body’s CD4+ T cell pool and progression to AIDS." (PMID 29250073, 2017). "In a prospective study of 398 adult patients with Acquired Immune Deficiency Syndrome (AIDS) on highly active antiretroviral therapy (HAART), those with VDD showed less recovery of CD4+ cells after 18 months of HAART." (PMID 28672783, 2017). "Other variables used in the analysis include the child’s participation in either domestic work or farm work and severity of HIV/AIDS expressed as the CD4 cell count of the PLWHA or WHO-HIV stage (for the PLWHA only analysis) as a measure of level of illness." (PMID 28969498, 2017). "CD4 counts are determined as part of routine clinical care, a CD4 count below 350 cells/μL (or an AIDS-defining illness) at diagnosis is defined as late presentation." (PMID 28968389, 2017). "As expected, interaction analyses showed that HIV-1 subtypes interacted multiplicatively with CD4 count at baseline to contribute to HIV/AIDS progression (interaction P < 0.001)." (PMID 28484257, 2017). "Viral load typically spikes during primary HIV infection, when the virus first establishes itself in host CD4+ cells, and towards the end of infection, when CD4+ cell concentrations crash and hosts progress to AIDS." (PMID 28250813, 2017). "At AIDS stage, as well as in the second macaque sampled at D65, CD8+ T-cells were almost completely depleted from the submucosa, while CD4+ T-cells increased at AIDS stage." (PMID 28579989, 2017). "This study identified characteristics of patients who delay ART initiation beyond the first two years of entering in care, which included an earlier CNICS enrollment date, higher CD4 count, lower viral load, and a prevalent AIDS diagnosis." (PMID 28700693, 2017). "The AIDS patients were characterized by a substantial decrease in the number of CD4+ T cells, and OTR patients had to be treated with immunosuppressants, so their T-lymphocyte counts were also low." (PMID 28035481, 2017). "Initially the number of AIDS incidents was estimated on the basis of CD4+ T-cell counts, viremia and CD4+/CD8+ ratio, which can lead to additional uncertainty of the estimated value due to scarcity of data regarding viremia and CD4+/CD8+ ratio." (PMID 29131849, 2017). "An increasing number of studies show that a low nadir CD4+ T-cell count (<50 cells/μl), is an unfavourable prognostic marker of diseases unrelated to AIDS." (PMID 28749986, 2017). "Historically, the initiation of ART was delayed until the onset of AIDS (i.e., when CD4+ cell density declines below 200 cells/mm3; WHO 2010)." (PMID 28250813, 2017). "Numerous studies have found that the loss of naïve CD4+ T cells occurs fairly early during HIV-1 infection and precedes the loss of immune homeostasis and AIDS progression." (PMID 28232735, 2017). "In the early 2000s, Brazilian guidelines recommended initiating ART for those with a CD4+ lymphocyte count below 200 cells/mm3 or with clinical manifestations of AIDS." (PMID 28348602, 2017).
AIDS (continued). "Changes over time in the CD4 initiation threshold can be found in the South African Department of Health’s, British HIV Association’s and European AIDS Clinical Society’s guidelines." (PMID 39450053, 2017). "A progressive decline to AIDS defining levels of CD4+ T cells occurred in P2A which succumbed to AIDS-like disease at 44 weeks p.i.." (PMID 28945790, 2017). "We observed consistent results in AIDS patients, whose CD4+ T lymphocytes were lower than 50/μL in 83.3% cases and lower than 200/μL in 96.7% cases." (PMID 28035481, 2017). "CD4 cell count is used with portable CD4 counters in resource-limited settings to manage HIV/AIDS patients." (PMID 29290885, 2017). "Late presentation (LP) at the time of HIV diagnosis is defined as presentation with AIDS whatever the CD4 cell count or with CD4 <350 cells/mm." (PMID 28209189, 2017). "We reported an uncommon case of an AIDS patient (6 CD4 + T cells/mm3) with both pulmonary and cerebral toxoplasmosis associated with pneumocystis pneumonia." (PMID 29258242, 2017). "In fact, recently it has been shown the potential clinical role of CD4/CD8 ratio as prognostic factor for serious non-AIDS events and death even in patients who were virologically suppressed after several years of antiretroviral therapy and CD4 recovery." (PMID 28264665, 2017). "Our findings are consistent with this in that we found the progression of frailty to be multifactorial, including having a low nadir CD4 cell count (or history of AIDS) and HCV co-infection." (PMID 28981535, 2017). "Among the class I loci, HLA-B alleles are the most polymorphic and have a major influence on CD4+ T lymphocyte count, viral set point, and therefore, on the rate of progression to AIDS." (PMID 28326304, 2017). "Acquired immunodeficiency syndrome (AIDS) is diagnosed when the CD4 T-cells level count drops below 200 cells/cm3 or when opportunistic infections arise." (PMID 29085399, 2017). "Previous studies demonstrated that HCMV viremia increases mortality in AIDS patients with low CD4 counts." (PMID 28467444, 2017). "The patients hospitalized with AIDS in this study presented a low CD4+ lymphocyte count (90% of patients had less than 200 cells/mm3) and a high viral load (80% of patients had above 50,000 copies/mL)." (PMID 28303122, 2017). "One AIDS study revealed that CD4+ T-cell counts in patients with local cryptococcosis were higher than in those with disseminated cryptococcosis." (PMID 28035481, 2017). "Previous research also found CD4+ T-lymphocyte counts lower than 50/μL in 78% and 200/μL in 97% of AIDS patients suffering from cryptococcosis." (PMID 28035481, 2017). "Baseline covariates were age, gender, transmission group, origin (sub-Saharan vs other), AIDS diagnosis at baseline, CD4 cell count and HIV RNA." (PMID 29202691, 2017). "Microbial translocation correlates with poor CD4+ T-cell recovery, HIV disease progression, and susceptibility to non-AIDS conditions such as CVD and neurocognitive impairment." (PMID 29209103, 2017). "The adjusted hazard ratio (aHR) for AIDS-related mortality for the lowest (vs middle) tertile of CD4:CD8 ratio was 1.28 (95% CI.95–1.73) and for the highest (vs middle) tertile of CD8 was 1.36 (95% CI, 1.01–1.84)." (PMID 28903507, 2017). "Advanced HIV before ART start was less frequent among the African than the Asian participants, with CD4 cell counts <100 cells/μl in 35% and 45%, respectively, and a history of AIDS in 15% and 51%, respectively." (PMID 28362063, 2017). "Literature reports demonstrate that CoQ10 supplementation has improved CD4 T cell counts in patients with AIDS and outcomes in herpes and HPV infections." (PMID 29456787, 2017). "AIDS at inclusion, a CD4 count < 350/μl and hepatitis C were independent predictors of patient death in the multivariate model." (PMID 28122494, 2017). "Those who present to care with a CD4 count below 200 cells/μL, or an AIDS-defining event, are considered to have advanced HIV disease." (PMID 27091128, 2016).
AIDS (continued). "Without intervention, these causal and contextual factors ultimately contribute to lower CD4 counts, greater progression to AIDS, and worse treatment outcomes." (PMID 27547750, 2016). "Second, the major target of HIV-1, CD4+ T cells, is progressively depleted, which eventually leads to AIDS." (PMID 26973648, 2016). "The prevalence of IPI was significantly higher in HIV/AIDS patients with CD4+ T cell count below 200 cells/μl." (PMID 26754404, 2016). "There are no data comparing the response to PI/r-based regimens in people presenting for care with low CD4 counts or AIDS (LC)." (PMID 27348592, 2016). "After being diagnosed and with a very low CD4 count, the doctor gave me a prescription which indicated that I should try one of the leading AIDS drugs, AZT." (PMID 27538792, 2016). "Longitudinal plots / survival curves can be used to view changes in CD4+ cell count, HIV viral load, hemoglobin, and other continuously varying measures and the probability of AIDS-defining events, loss to follow-up, death, and other endpoints." (PMID 26963255, 2016). "Acquired immunodeficiency syndrome (AIDS) is a complex and multifaceted disease that arises from the infection of CD4+ T-cells by the human immunodeficiency virus (HIV-1)." (PMID 27060080, 2016). "Participants who got lost to follow-up also presented with significantly higher CD4 counts at their last visit than study participants who were at their next visit diagnosed with AIDS and who received HAART (p < 0.0001)." (PMID 26812052, 2016). "AIDS is defined as having a CD4+ T cell count below 200 cells per μL or displaying specific clinical presentations in association with an HIV infection." (PMID 28050553, 2016). "Among HIV-positive men, neither HSIL-AIN2 nor HSIL-AIN3 outcomes were significantly associated with most recent CD4+ T-cell count, HIV viral load, ART treatment status or a history of AIDS defining illness." (PMID 29074193, 2016). "AIDS mortality was strongly related to lower CD4 count and viral replication at ten years after starting ART." (PMID 27525413, 2016). "CART patients featured lower CD4 nadir (p < 0.0001) and CD4 count at time of analysis (p = 0.003), displayed higher proportion of AIDS diagnosis (p = 0.003) and longer HIV infection (p < 0.0001)." (PMID 28066424, 2016). "On the contrary, in these chronic SIV-infected macaques before the development of AIDS-related diarrhea, both CD4+ T cells and CD8+ T cells expressed higher immune activation markers CD69 and HLA-DR in the peripheral blood." (PMID 27708644, 2016). "During the development of ART, recombinant IL-2 has been trialed as adjunctive AIDS treatment by boosting CD4+ T cell numbers during ART." (PMID 27391012, 2016). "All patients newly HIV diagnosed in CRC between January 2010 and December 2014 were included an initial CD4 count <350 cells/cmm or an AIDS-defining illness within 6 months after diagnosis defined late presenters (LP)." (PMID 27356504, 2016). "An inverse relationship between occurrence of cryptosporidiosis and CD4 T cell count has been well documented in many studies in patients with AIDS." (PMID 26981284, 2016). "This endpoint was reached if CD4 counts dropped below 200 cell/μl (CDC stage 3) or if an AIDS-defining condition occurred (CDC stage C), or if the patient died." (PMID 26812052, 2016). "We estimated overall and cause-specific mortality rate ratios for age, sex, transmission through injection drug use, AIDS, CD4 count and HIV-1 RNA." (PMID 27525413, 2016). "As the HIV-positive patient reaches the low end of CD4 spectrum and manifests AIDS, this puts the patient in a further immunocompromised state, opening the doors to a multitude of opportunistic infections and neoplasia." (PMID 27747712, 2016). "Regular screening and treatment for intestinal parasites and the strengthening of adherence to ART to increase the CD4+ T cell counts is of prime importance to improve the overall wellbeing of HIV/AIDS patients in this study area." (PMID 26754404, 2016).